CXCR4 (C-X-C motif chemokine receptor 4)
Diseases named in the same sentence as CXCR4 in open-access papers (continued):
Sharing a sentence is not in itself a finding about the gene and the disease.
WHIM syndrome (90 papers, 2009 to 2026). "Warts, hypogammaglobulinemia, infections, and myelokathexis (WHIM) syndrome is an immunodeficiency caused by autosomal dominant hyperfunctional mutations in chemokine receptor CXCR4 that promote panleukopenia due to BM retention." (PMID 41505207, 2026). "Whole-exome sequencing identified a heterozygous de novo CXCR4 frameshift mutation (c.1172_1173del), confirming the diagnosis of WHIM syndrome." (PMID 41629964, 2026). "Gain-of-function (GOF) variants in CXCR4 are associated with WHIM syndrome, characterized by neutropenia, lymphopenia, frequent infections, warts, and myelokathexis." (PMID 41451234, 2025). "Warts, Hypogammaglobulinemia, Infections, and Myelokathexis (WHIM) syndrome is a rare immunodeficiency caused by gain‐of‐function mutations in the chemokine receptor CXCR4." (PMID 40202253, 2025). "WHIM syndrome is typically caused by C-terminal gain-of-function variants in CXCR4, yet clinical heterogeneity suggests additional genetic modifiers." (PMID 40909287, 2025). "Plerixafor mobilizes sequestered leukocytes in WHIM syndrome by antagonizing pathogenic CXCR4 signaling." (PMID 41141324, 2025). "Given the significant role of CXCR4 GOF variants in the pathogenesis of WHIM syndrome, CXCR4 antagonists have emerged as a promising therapeutic strategy." (PMID 41451234, 2025). "Gain-of-function (GOF) variants in the CXCR4 gene are primarily associated with WHIM syndrome, a condition that falls under the umbrella of SCN." (PMID 41451234, 2025). "WHIM syndrome is a rare primary immunodeficiency disorder associated with chronic neutropenia resulting from mutations in the CXCR4 gene that impair receptor function." (PMID 40430547, 2025). "Warts hypogammaglobulinemia immunodeficiency myelokathexis syndrome (WHIM syndrome) demonstrates how CXCR4 gain-of-function mutations (e.g., p.V320FS342X) impair leukocyte trafficking through abnormal bone marrow retention." (PMID 41141324, 2025). "Previous studies have identified 26 autosomal dominant mutations in CXCR4 associated with WHIM syndrome." (PMID 39035006, 2024). "It was recently reported that CXCR4 GOF mutations lead to a more severe depression of circulating CD8+ T-cell counts compared with CD4+ T cells in patients with WHIM syndrome and in a WHIM mouse model." (PMID 39588369, 2024). "Warts, Hypogammaglobulinemia, Infections, and Myelokathexis (WHIM) syndrome is a rare primary immunodeficiency disease in humans caused by a gain of function in CXCR4, mostly due to inherited heterozygous mutations in CXCR4." (PMID 39226327, 2024). "It is therefore likely that additional novel variants will be identified in individuals with WHIM syndrome in the future, especially due to many possible combinations of indels leading to frameshift variants in the C-terminus of CXCR4." (PMID 39040098, 2024). "In this study we present a Chinese family (designated P1–P4, corresponding to P37-P40 in a large WHIM syndrome cohort) with WHIM syndrome caused by a CXCR4 C-terminal variant." (PMID 39575248, 2024). "In patients with WHIM syndrome, CXCR4 GOF mutations cause increased retention of neutrophils in the BM, and this process is thought to contribute to circulating neutropenia." (PMID 39588369, 2024). "In the current study, the effects of CXCR4 antagonism on leukocyte trafficking and distribution in primary and secondary lymphoid organs were investigated in a mouse model of WHIM syndrome carrying the heterozygous Cxcr41013 mutation." (PMID 39588369, 2024). "Past research identified dominant mutations in the CXCR4 gene that are inheritable and result in a gain-of-function of CXCR4 protein function, which causes the symptoms of the WHIM syndrome." (PMID 39226327, 2024). "Several previous studies on CXCR4 gene reported multiple mutations that are associated with certain diseases such as WHIM syndrome and Waldenström’s Macroglobulinemia." (PMID 39715225, 2024).
WHIM syndrome (continued). "This article provides an overview of the spectrum of CXCR4 variants in WHIM syndrome and summarizes the various lines of clinical and functional evidence that can support interpretation of newly identified variants." (PMID 39040098, 2024). "Heterozygous autosomal dominant mutations in the CXCR4 gene cause WHIM syndrome a severe combined immunodeficiency disorder characterized by increased susceptibility to human papillomavirus pathogenesis, resulting in warts, condyloma acuminata and carcinomas." (PMID 39035006, 2024). "While CXCR4 gain-of-function variants are the most common cause of WHIM syndrome, a proportion of patients remain undiagnosed." (PMID 39035006, 2024). "Detection of a pathogenic CXCR4 variant in an affected individual supports the diagnosis of WHIM syndrome but relies on an appropriate annotation of disease-causing variants." (PMID 39040098, 2024). "WHIM syndrome is most often caused by gain-of-function mutations in the gene encoding C-X-C chemokine receptor 4 (CXCR4)." (PMID 39588369, 2024). "Complementary to this experiment, the consequences of CXCR4 gain of function were examined in CXCR4+/1013 mice with the heterozygous CXCR4 mutation characteristic of the Warts, Hypogammaglobulinemia, Infections, and Myelokathexis (WHIM) syndrome." (PMID 38291527, 2024). "These defects in leukocytes from individuals with WHIM syndrome can be utilized as evidence for a deleterious effect associated with newly identified CXCR4 variants." (PMID 39040098, 2024). "Heterozygous C-terminal CXCR4 variants are found in ≈90% of individuals with clinical diagnosis of WHIM syndrome." (PMID 39040098, 2024). "Heterozygous autosomal dominant mutations in the CXCR4 gene cause WHIM syndrome, a severe combined immunodeficiency disorder." (PMID 39035006, 2024). "A knock-in mouse strain with a WHIM syndrome-related mutation in Cxcr4 gene (CXCR41013) was created to study underlying mechanisms of CXCR4 mutation caused WHIM pathogenesis." (PMID 39226327, 2024). "Remarkably, mutations truncating this C-terminal tail have been linked to the acquisition of enhanced CXCR4 function, a hallmark of WHIM syndrome (see paragraph “WHIM syndrome”)." (PMID 38519141, 2024). "WHIM syndrome is most often caused by gain-of-function (GOF) mutations in the gene encoding C-X-C chemokine receptor 4 (CXCR4), a master regulator of immune cell trafficking, homeostasis, and organogenesis." (PMID 39588369, 2024). "Warts, hypogammaglobulinemia, infections, and myelokathexis (WHIM) syndrome is a primary immunodeficiency disorder caused by heterozygous gain-of-function CXCR4 mutations." (PMID 37561579, 2023). "Like other known mutations causing WHIM syndrome, L317fsX3 affects the C-terminal domain of CXCR4, where a frameshift removes the last 33 amino acids, including 16 of the 18 serine and threonine residues." (PMID 36883568, 2023). "WHIM syndrome (OMIM 193670) is a rare inherited disorder of immunity caused by autosomal dominant heterozygous mutations in CXCR4." (PMID 36883568, 2023). "WHIM syndrome is an inherited immune disorder caused by an autosomal dominant heterozygous mutation in CXCR4." (PMID 36883568, 2023). "In the present study, we describe what we believe to be a novel heterozygous frameshifting mutation, L317fsX3, in the C-terminus of CXCR4 identified in a single Portuguese family with the classical WHIM syndrome autosomal dominant pattern of inheritance." (PMID 36883568, 2023). "We describe what we believe to be a novel CXCR4 mutation, Leu317fsX3, associated with a form of WHIM syndrome, characterized by neutropenia and myelokathexis, but normal lymphocyte count and immunoglobulin levels." (PMID 36883568, 2023). "Accordingly, we screened published reports to gather the collection of known pathogenic CXCR4 mutations in patients with WHIM syndrome." (PMID 36089616, 2022).
WHIM syndrome (continued). "Such analysis would also be informative to identify potential biomarkers for WHIM syndrome diagnosis and to reclassify CXCR4 variants of uncertain significance." (PMID 36089616, 2022). "We used cell-based assays to analyze CXCL12-induced receptor trafficking and downstream signaling of 14 pathogenic CXCR4 variants previously identified in patients with WHIM syndrome." (PMID 36089616, 2022). "Previous studies have identified a total of 11 autosomal dominant mutations in CXCR4 across 105 patients that result in WHIM syndrome with the most prevalent being a truncation after Lys333 (R334X)." (PMID 34973340, 2022). "Based on our cohort and prior reports, CXCR4 variants linked to WHIM syndrome are located in the region of p.318–346." (PMID 35947323, 2022). "Based on these data, we propose that CXCL12-induced CXCR4 internalization can be used as a key parameter for the assessment of CXCR4 variant pathogenicity in vitro and as a potential disease biomarker for WHIM syndrome diagnosis." (PMID 36089616, 2022). "In WHIM syndrome, constitutive CXCR4 activation causes neutrophils to be retained in the bone marrow, while in a zebrafish model of WHIM, neutrophils are retained in the CHT." (PMID 35099005, 2022). "The receptor desensitization defect is believed to be a hallmark of CXCR4 mutations found in WHIM syndrome patients and is the mechanism responsible for their gain-of-function phenotype." (PMID 35947323, 2022). "WHIM syndrome mainly results from heterozygous gain-of-function mutations in the chemokine receptor CXCR4, a 352 amino acid G-protein-coupled receptor (GPCR) that contains a Ser/Thr-rich C-terminal tail that is a primary region of regulation." (PMID 34973340, 2022). "Taken together, our studies provide insight on a new mutation in CXCR4 that results in WHIM syndrome and help to define the mechanisms involved in the altered regulation of WHIM mutants including S339fs5 and R334X." (PMID 34973340, 2022). "As genetic testing has become more readily available, sequencing for pathogenic gain-of-function variants in the C terminal region of the CXCR4 gene is often used to confirm a clinical suspicion of WHIM syndrome." (PMID 35947323, 2022). "WHIM syndrome, an extremely rare congenital disease with combined immunodeficiency, is mainly caused by heterozygous gain-of-function mutation in the CXCR4 gene." (PMID 35493524, 2022). "CXCR4 gene gain of function mutations in WHIM syndrome lead to a phenotype of combined immunodeficiency and abundant mature apoptotic neutrophil accumulation in bone marrow, or myelokathexis, resulting in neutropenia in peripheral blood." (PMID 34697698, 2022). "The CXCR4 somatic mutations in WM are identical to the germline variants found in a rare disease called WHIM syndrome (warts, hypogammaglobulinemia, infection, and myelokathexis), thus a mutated CXCR4 is denoted CXCR4WHIM." (PMID 35950210, 2022). "Infections, such as other CXCR4 WHIM syndrome variants, include human papillomavirus-associated disease including warts and mucosal intraepithelial lesions." (PMID 34973340, 2022). "WHIM syndrome is a congenital immunodeficiency disorder that is caused by functional overactivity of CXCR4, and manifests in e.g., retention of mature neutrophils in the BM, which in turn leads to neutropenia and increased risk of infections." (PMID 33980979, 2021). "This process, together with the impaired desensitization of CXCR4, causes the gain of CXCL12/CXCR4 function that characterizes WHIM syndrome." (PMID 33466410, 2021). "WHIM syndrome is an extremely rare autosomal dominant primary immunodeficiency that results from heterozygous gain-of-function mutations in the chemokine receptor CXCR4." (PMID 33918597, 2021). "The truncated CXCR4 lost phosphorylation sites impairs the desensitization process, thereby enhancing the activation of G-protein, and causing WHIM syndrome." (PMID 33485325, 2021).
WHIM syndrome (continued). "Considering that the WHIM syndrome is caused by gain of function mutations in CXCR4 gene, these observations support the critical role of GRKs in controlling this chemokine receptor’s functions." (PMID 33466410, 2021). "Warts, hypogammaglobulinemia, infections, and myelokathexis (WHIM) syndrome is usually caused by a gain-of-function mutation in the CXCR4 gene, which is in chromosome 2." (PMID 34868061, 2021). "Truncating germline mutations in the C-terminus of CXCR4 have been shown to act as gain-of-function mutations and cause WHIM syndrome (warts, hypogammaglobulinemia, infections, and myelokathexis), and Waldenström’s macroglobulinemia." (PMID 34368645, 2021). "Warts, hypogammaglobulinemia, recurrent bacterial infections and myelokathexis (WHIM) syndrome is a primary immunodeficiency disease (PID) usually caused by autosomal dominant mutations in the chemokine receptor CXCR4 gene." (PMID 33485325, 2021). "In WHIM syndrome, all but one of the CXCR4 germline mutations truncate receptor C-ter by premature termination (4 NS) or by frame-shifts (4 FS) that introduce from 3 to 24 additional new amino acids." (PMID 32784523, 2020). "Mutations in the C-term tail of the CXCR4 gene cause WHIM syndrome, a rare congenital immunodeficiency associated by chronic leukopenia." (PMID 32784523, 2020). "This further supports the general understanding of WHIM syndrome as an immunodeficiency caused by functional hyperactivity of CXCR4." (PMID 32784523, 2020). "All 17 CXCR4 heterozygous mutations identified so far in WM span in the C-ter of the receptor, and closely resemble the already documented germline mutations of CXCR4 C-ter occurring in heterozygosis in WHIM syndrome." (PMID 32784523, 2020). "WHIM syndrome is caused by a genetic mutation of the CXCR4 gene causing a gain-of-function and consequently an impairment of neutrophil mobilization from the BM that ultimately results in blood neutropenia." (PMID 33240898, 2020). "WHIM syndrome is a rare inherited primary immunodeficiency disorder caused by autosomal dominant gain-of-function mutations in the CXCR4 gene." (PMID 30791675, 2019). "The importance of this receptor in cellular trafficking to the BM was also highlighted in 2003 when GOF mutations in the CXCR4 gene were revealed as the mechanism for the sequestration of leukocytes in BM compartments of patients with WHIM syndrome." (PMID 31231387, 2019). "Dysregulation of CXCR4 function can result in cancer progression and metastasis, immunodeficiency diseases (particularly WHIM syndrome which is characterised by mutations in CXCR4), and neurodevelopmental defects." (PMID 31578415, 2019). "NK cells isolated from patients with WHIM syndrome carry gain-of-function (GOF) mutations in CXCR4 (CXCR4R334X)." (PMID 31231387, 2019). "CXCR4 signaling has been found to play an important role in regulating neutrophil retention in the CHT in the WHIM syndrome, where neutropenia has been linked to increased susceptibility to infection in patients as well as in the zebrafish model." (PMID 30787324, 2019). "The warts, hypogammaglobulinemia, infections, and myelokathexis (WHIM) syndrome is caused by dominant mutations in chemokine receptor CXCR4 that induce the truncation of its carboxy-terminal domain." (PMID 30233640, 2018). "The Warts, Hypogammaglobulinemia, Infections, Myelokathexis (WHIM) syndrome is an immunodeficiency caused by mutations in chemokine receptor CXCR4." (PMID 28928741, 2017). "Patients with GOF mutations in CXCR4, resulting in WHIM syndrome, have been treated successfully with the CXCR4 antagonist plerixafor." (PMID 28791010, 2017). "In order to analyze the B cell response defects that characterize the WHIM syndrome, we utilized a knock-in mouse strain (CXCR4+/1013) that harbors a WHIM-associated dominant mutation of the Cxcr4 gene (WHIM knock-in mice)." (PMID 28928741, 2017).
WHIM syndrome (continued). "Autosomal dominant mutations in CXCR4 that prevent receptor inactivation can lead to Wart, Hypogammaglobulinemia, Infection, and Myelokathexis, or WHIM syndrome." (PMID 28207860, 2017). "The wart, hypogammaglobulinemia, infection, and myelokathexis (WHIM) syndrome is associated with inherited gain-of-function mutations in the CXCR4 gene that encodes a receptor for the CXCL12 chemokine." (PMID 27918748, 2016). "The warts, hypogammaglobulinemia, infections, and myelokathexis (WHIM) syndrome is caused by mutations in CXCR4, a chemokine receptor that in mutant form leads to impairment of APC–T cell interactions." (PMID 26379669, 2015). "These are remarkably similar to truncating mutations in CXCR4 that have been described as exacerbating signaling in WHIM syndrome patients." (PMID 25981299, 2015). "In principle, with Plerixafor/AMD3100 an approved CXCR4 antagonist is available, which seems to be well-tolerated at least for several months as tested in patients with a gain of function mutation in CXCR4 (WHIM syndrome)." (PMID 25152735, 2014). "Nef also profoundly downregulated the naturally truncated CXCR4 associated with WHIM syndrome and engineered variants of CXCR4 that resist CXCL12 induced internalization via an ubiquitinylation independent mechanism." (PMID 24489825, 2014). "Mutations in the CXCR4 gene affecting C-terminal phosphorylation sites are a hallmark of WHIM syndrome, a genetic disorder characterized by a gain-of-CXCR4-function." (PMID 23734232, 2013). "We then asked if the S346-8A mutation perturbs CXCR4 function like CXCR4 mutations causing WHIM syndrome and compared the S346-8A mutant with the E343K WHIM mutant and wildtype CXCR4." (PMID 23734232, 2013). "Most WHIM syndrome patients carry heterozygous mutations in the CXCR4 gene which eliminate the last 10 to 19 residues of the C terminus." (PMID 23734232, 2013). "To this end, we used two CXCR4 mutants with an N-terminal T7-tag and deletions of the last 10 and 17 C-terminal residues (CXCR4-Δ10, CXCR4-Δ17), which correspond to WHIM syndrome-associated mutations in the human CXCR4 gene." (PMID 23734232, 2013). "Hierarchical organization of CXCR4 phosphorylation explains why small deletions at the extreme CXCR4 C terminus typically associated with WHIM syndrome severely alter CXCR4 function." (PMID 23734232, 2013). "The causal connection between WHIM syndrome and dysregulated CXCR4 signaling has been confirmed in knockin mice carrying a heterozygous R334X truncation mutation, which corresponds to the most frequent WHIM syndrome-causing mutation in humans." (PMID 23734232, 2013). "In the current study, we have dissected the early events that follow ligand binding to the CXCR4 receptor to identify deficiencies stemming from a mutant CXCR4, which is missing the 19 carboxy-terminal residues and is associated with WHIM syndrome." (PMID 19956569, 2009). "This is the most extensive CXCR4 truncation associated with WHIM syndrome, which derived from a frame shift mutation (previously designated WHIM R334X)." (PMID 19956569, 2009). "This study was a retrospective review of medical records from a United States National Institutes of Health natural history cohort of patients with WHIM syndrome seen between 2005 and 2024, including a cross‐sectional analysis of cutaneous manifestations and CXCR4 variants." (PMID 40202253, 2025). "As per European Society for Immunodeficiencies–Pan-American Group for Immunodeficiency diagnostic criteria, identification of a CXCR4 variant in the intracellular C-terminal tail of the receptor or an activating CXCR4 variant supports the definitive diagnosis of WHIM syndrome." (PMID 39040098, 2024). "Consequently, the gain of function mutations in the CXCR4/CXCL12 signaling axis of WHIM syndrome patients, are associated with panleukopenia and neutrophil retention in bone marrow." (PMID 39226327, 2024).